BMAL1 (basic helix-loop-helix ARNT like 1)
Diseases named in the same sentence as BMAL1 in open-access papers (continued):
Sharing a sentence is not in itself a finding about the gene and the disease.
tumor (continued). "More recently, the presence of a non-metastatic melanoma tumor in mice was shown to reduce Bmal1 and increase cFos gene expression in the SCN compared to control animals, suggesting that molecules released from the tumor may affect the SCN as well peripheral tissue clocks." (PMID 33683376, 2021). "In addition, the myelocytomatosis oncogene cellular homolog (Myc) proto-oncogene is thought to be regulated by BMAL1/neuronal PAS domain protein 2 (NPAS2) (a CLOCK paralogue) action on its E-boxes, which may contribute to enhanced tumor growth in Per2 mutant mice in response to DNA damage." (PMID 31039152, 2019). "In mice lacking BMAL1 or with disrupted circadian rhythms, there is increased YAP/TEAD activity alongside weakened Wnt signaling, which makes intestinal tumor stem cells more prone to rapid proliferation." (PMID 40821111, 2025). "Unlike the mixed roles of CLOCK and BMAL1 in CSCs, period circadian regulator genes (e.g., PER2 and PER3), generally known as tumor suppressors in various types of cancer, have been shown to inhibit CSC maintenance and survival in tumors." (PMID 36430659, 2022). "Scatter plot analysis showed a negative relationship between mRNA expression levels of BMAL1 and GPAM in tumor tissues from 30 HCC individuals." (PMID 36439870, 2022). "Compared to cells expressing luciferase only, BMAL1-expressing HepG2 and SNU449 cells were significantly retarded in tumor growth, resulting in a complete lack of tumor growth or substantially smaller tumors." (PMID 30341289, 2018). "In contrast, tumor volumes were indistinguishable between DEX- and PBS-treated mice harboring Bmal1 shRNA tumors." (PMID 28196531, 2017). "Additionally, we confirmed that hypoxia-mediated decrease of BMAL1 was prevented by inhibiting LDH-A and tumor acidosis using oxamate, non-competitive LDH inhibitor, and small interfering RNA." (PMID 32316196, 2020). "Furthermore, a series of core clock and output genes (BMAL1, ARNTL and PER1,2) have been identified with the anti-tumor effects which are subject to the regulation through a non-genetic route, e.g. epigenetic changes." (PMID 26843619, 2016).
cancer (185 papers, 2009 to 2025). A tumor composed of atypical neoplastic, often pleomorphic cells that invade other tissues. "Various studies have detected mutated or dysregulated core CCGs including Clock and Bmal1 in cancer cells." (PMID 40495887, 2025). "Even so, increased cancer susceptibility is also located in clock genes rs117104877, rs2290035, rs2278749, and rs969485 in BMAL1 and rs3749474 and rs11943456 in CLOCK." (PMID 38892035, 2024). "Specifically, BMAL1 is critical in hematologic malignancies, where its inactivation has been linked to the advancement of cancers." (PMID 38469551, 2024). "Cryptochromes, Periods, and Bmal1 are circadian clock genes that have been linked to aging and cancer." (PMID 38725697, 2024). "Circadian disruption enhances the risk of several cancer types 43 and deletion of BMAL1 has been used to study circadian disruption genetically, with mixed results in mouse models of cancer 2–4,44." (PMID 39070610, 2024). "One of the important core circadian clock gene, “BMAL1” has been found to regulate the molecular processes, thereby preventing or decreasing the risk of cancer progression." (PMID 37503323, 2023). "Several studies have demonstrated that core clock genes, including Bmal1 and Clock, are commonly dysregulated or mutated in cancer cells." (PMID 36595671, 2023). "We further investigated the association of candidate cancer-related genes clock (Bmal1 and Cry1/2) genes." (PMID 31523185, 2019). "Targets specific to BMAL1 were enriched in a wide variety of processes associated with protein assembly, nucleic acid metabolism as well as renin-angiotensin, hormone and cancer signaling." (PMID 21731503, 2011). "We found that when kept in 24 hour alternating light-dark conditions (24hr LD cycles), mice deficient in Bmal1 (Bmal1+/−), Cry1 and Cry2 (Cry1−/−;Cry2−/−), Per1 and Per2 (Per1−/−;Per2m/m) or Per2 alone (Per2−/−) were all cancer-prone." (PMID 20539819, 2010). "Dysregulation of BMAL1 expression and function has been implicated in various diseases, including neurodegenerative disorders, chronic airway diseases, diabetes, and cancer." (PMID 40638681, 2025). "BMAL1 is widely linked to aging, cardiovascular disease, immunological disorders, and cancer." (PMID 38892035, 2024). "The disruption of the circadian rhythm in mice, either by deleting the Bmal1 gene or through chronic jet lag, exacerbates fibrotic phenotype in tumors, promoting cancer metastasis in pancreatic cancer, involving cancer-associated fibroblasts and transforming growth factor (TGF-β) signaling pathway." (PMID 39062777, 2024). "This suggested that BMAL1 may have cellular context-dependent functions, underlining the complexity of the circadian clock components in cancer biology." (PMID 38951864, 2024). "Therefore, focusing on these immune responses associated with CLOCK and BMAL1 should provide new insights into cancer treatment." (PMID 36647780, 2023). "Similarly, the output from Bmal1/Clock signaling, i.e., Per1-3, is also commonly reduced in cancer cells and associated with more advanced disease and poor prognosis." (PMID 34958429, 2021). "Clinical studies reporting associations between BMAL1 and cancer are limited." (PMID 33302582, 2020). "However, as seen for other circadian clock genes, there are different findings from different laboratories showing both pro- and anti-cancer effects of BMAL1 KO mutation." (PMID 33114365, 2020). "However, induction of apoptosis before transformation or during eradication of cancer cells for therapeutic purposes should be considered in overall effect of BMAL1 mutations." (PMID 30375470, 2018). "Our previous studies identified CLOCK/BMAL1 transcriptional activity as a target for pharmacological intervention to, among other potential applications, reduce the toxicity associated with genotoxic anti-cancer treatments." (PMID 22249125, 2011). "This study further identifies ALDH3A1 as a key downstream effector molecule of BMAL1 and a potential target for cancer therapy." (PMID 41228459, 2025).
cancer (continued). "Building on the identified temporal circadian dynamics within and across cancer subtypes, we next assessed Bmal1-Per2 phase differences over time." (PMID 39994450, 2025). "The differential roles of BMAL1 in various cancers and cellular senescence, along with the complexity of its regulatory network, make it a potential target for anticancer therapies." (PMID 40046513, 2025). "Co-citation networks bridged molecular chronobiology (Science, PNAS) and clinical oncology (Cancer Research), though mechanistic studies prioritized clock genes (e.g., BMAL1, PER2) over environmental disruptors." (PMID 40589644, 2025). "When BMAL1 expression or function is disrupted, it can lead to cell cycle imbalance, DNA damage accumulation, and increased oxidative stress, thereby promoting cancer development." (PMID 40046513, 2025). "Recently, the significance of BMAL1 in tumorigenesis and cancer therapy has garnered heightened attention." (PMID 40638681, 2025). "CRGs like BMAL1 are involved in the regulation of oxidative phosphorylation and glycolysis pathways, which are often altered in cancer cells to meet their increased energy demands." (PMID 40191195, 2025). "In a separate study, the ablation of BMAL1 expression in intestinal epithelium was correlated with an increased initiation of cancer in mouse intestinal organoids." (PMID 38607733, 2024). "Collectively, these findings illuminate the significant role of circadian rhythm, particularly the circadian protein BMAL1, in orchestrating molecular events that impact cancer metastasis." (PMID 38361941, 2024). "After conducting experiments on the impact of BMAL1 on the sensitivity of certain frrst-line cancer treatment drugs, we observed that knocking down BMAL1 increased the sensitivity of AML cells to the drugs venetoclax, dasatinib, and sorafenib." (PMID 38703241, 2024). "This dual function of BMAL1 on carcinogenesis was also observed for other cancer entities such as colorectal cancer." (PMID 38378853, 2024). "In vitro and in vivo of cancer researches, it showed that Bmal-1 deletion promoted the antitumor effects of ferroptosis activators." (PMID 39296207, 2024). "In HCC, the fetal variant of P2-HNF4α, typically upregulated, significantly alters the expression of BMAL1, influencing cancer progression dynamics." (PMID 39061191, 2024). "On the other hand, various works have found that the selective autophagic degradation of the circadian clock regulators (mainly BMAL1) named as clockophagy can promote ferroptotic cancer cell death in vitro and in vivo." (PMID 39199335, 2024). "Alterations in the components of the circadian clock, including BMAL1, PER1/2, and CRY1/2, have been correlated with an increased risk of cancer development." (PMID 38469551, 2024). "There is growing recognition that the roles of CLOCK and BMAL1 in the development of cancer vary significantly depending on the context and type of disease." (PMID 39001398, 2024). "Data from the Cancer Dependency Map (DepMap) 29,30 shows that deletion of BMAL1 reduces survival of RCC cells, indicating that BMAL1 supports growth and/or survival of RCC cells." (PMID 39070610, 2024). "In different cancers, BMAL1 has different or even opposite effects on the function of the immune system, in agreement with the contradictory points proposed above." (PMID 36647780, 2023). "In fact, these opposing effects of Bmal1 in cancer cells and in host stromal cells are functionally in harmonized concordance in cancer metastasis." (PMID 37330661, 2023). "Because CAFs are involved in cancer invasion and metastasis, we studied the impact of Bmal1 deletion in cancer hosts on cancer metastasis." (PMID 37330661, 2023). "Perhaps, cancer cells utilize BMAL1‐targeted gene products to support their growth, invasion, and metastasis." (PMID 37330661, 2023). "This metastasis‐promoting effect of cancer cell–derived Bmal1 opposes the host stromal cell–expressed Bmal1‐regulated cancer metastasis." (PMID 37330661, 2023).
cancer (continued). "So far, several reports have stated that Bmal1 is a relevant transcription factor capable of suppressing the proliferation, migration, and invasion of several cancer cells." (PMID 37504857, 2023). "Brain and muscle ARNT‐like protein 1 (BMAL1) is an important biological proteins that can regulate the behavior of cancer cells and their response to chemotherapy." (PMID 36806631, 2023). "Mice with genetic disruptions of Per2, Bmal1, Cry1, and Cry2, which are regulatory factors of the circadian clock, spontaneously developed cancer in multiple organs, including the liver and ovaries." (PMID 37524704, 2023). "Other small synthetic molecules, agonists of the nuclear receptors REV-ERBs (SR9011 and SR9009) that inhibit Bmal1 transcription under normal conditions, are lethal in different cancers including GBM." (PMID 36796229, 2023). "g., channel proteins), RNA sequencing identified several enriched pathways integral to cancer progression and chemoresistance in the Bmal1 functional knockout cells, such as the PI3K-AKT pathway." (PMID 37262074, 2023). "On the other hand, there is evidence in both directions on a role for BMAL1 in cancer progression, probably indicating the heterogeneity in cancer itself." (PMID 36731029, 2023). "BMAL1 overexpression downregulates cyclin B, a cell cycle regulator, which leads to cancer cell proliferation." (PMID 36731029, 2023). "The increased susceptibility to this anticancer drug was mediated by TERT (Telomerase Reverse Transcriptase), a downstream gene of Bmal1, whose activity was found to be under circadian control and widely activated in cancer." (PMID 37504857, 2023). "The ectopic recruitment of BMAL1 to thousands of additional binding sites drives essential hallmarks of cancer progression in these cells, including ramped-up metabolism and proliferative activity and maintenance of CSC state." (PMID 36937362, 2023). "Collectively, our observations support the concept that anti-apoptosis activity of the cancer-specific WEE1 contributes to BMAL1::CLOCK stimulated HCC cell proliferation." (PMID 36595671, 2023). "During the past decades, a wide range of studies have shown that dysregulations of circadian rhythms genes, including Clock, Period 1, Period 2 and Period 3, and Bmal1, play essential role in the development of various cancers." (PMID 37003979, 2023). "Although, HIF-1α is associated with poor prognosis in cancer and CVD, it works synergistically with one of the core regulators of the circadian rhythm—basic helix-loop-helix ARNT like 1 (BMAL1)." (PMID 37511104, 2023). "Another study using in vitro and in silico models linked irinotecan cytotoxicity, a drug for colorectal cancer, to clock gene Bmal1 expression, putting in evidence a role for circadian rhythms in cancer treatment." (PMID 37504857, 2023). "In support of these findings, a significant relationship has been established between different types of cancer, such as breast, lung and prostate cancer, and variations in Bmal1, Clock, RORα and RORβ." (PMID 36768253, 2023). "Meanwhile, BMAL1/CLOCK knockdown induces the downregulation of the WEE1 gene, which encodes a checkpoint kinase essential for cancer cells’ survival and, consequently, leads to enhanced genome instability and apoptosis." (PMID 36937362, 2023). "Co‐implantation of cancer cells and CAFs at the ratio of 1:1 resulted in marked increases of metastatic incidences in both Bmal1+/+ and Bmal1−/− mice." (PMID 37330661, 2023). "Genetic studies demonstrated that transcriptional regulation of WEE1 and p21 cooperatively contributes to cancer cell proliferation promoted by BMAL1::CLOCK." (PMID 36937362, 2023). "Specifically, disrupting PER2, CRY2, or BMAL1 in various tissues can increase the likelihood of cancer development." (PMID 35356228, 2022). "Evidence regarding the role of the REV-ERB-targeted gene BMAL1 in cancer cell biology is conflicting." (PMID 36357378, 2022).
cancer (continued). "The four integral clock proteins, PER, CRY, BMAL1, and CLOCK, all have complex molecular roles that can improve our understanding of cancer risk and biologically/clinically relevant outcomes." (PMID 35356228, 2022). "Nevertheless, the biological functions of BMAL1, especially its role in lipid metabolism reprogramming in cancer cells, remain elusive." (PMID 36439870, 2022). "Nevertheless, the biological functions of BMAL1, especially its precise role in lipid metabolism reprogramming in cancer cells, remain elusive." (PMID 36439870, 2022). "Together, FLIM data and metabolomics analyses illustrate that transformed Apc+/−;Bmal1−/− organoids exhibit heightened glycolytic metabolism and activation of branch point pathways that are required to sustain enhanced growth of cancer cells." (PMID 35947664, 2022). "Rev-erbα, a known circadian modulator playing a pivotal role in the cyclic Bmal1 and CLOCK transcription, has been implicated in a variety of physiological and pathophysiological processes, such as metabolism, cancers, and inflammatory responses." (PMID 35668454, 2022). "Since loss of E-cadherin is a key feature of EMT in various cancers, the E-cadherin expression patterns in the three CRC cell lines were first analyzed to assess the impact of BMAL1-KD on the EMT process." (PMID 34065633, 2021). "In cancer cell lines, REV-ERBα up-regulation is associated with protooncogene MYC followed by reduced BMAL1 levels and loss of circadian control of glucose metabolism." (PMID 34948470, 2021). "The most consistent evidence across multiple cancer types (lending greater clinical relevance) appears to be with BMAL1 and glucocorticoid expression levels." (PMID 33794967, 2021). "These stem and cancer cells retain robust rhythms, and deletion of core clock components such as BMAL1 restrained or even reversed tumorigenesis, particularly in stem-like cells." (PMID 34299381, 2021). "miR-155 has a number of effects important to SARS-CoV-2 pathophysiology and anti-viral/cancer responses, including Bmal1 suppression, and therefore suppression of the Bmal1/PDC/OXPHOS/TCA cycle linked to increased acetyl-CoA production." (PMID 32867244, 2020). "Across different cancers, we observed that the negative regulatory genes are downregulated while the positive regulatory genes, such as BMAL1 and CLOCK, show minimal alterations." (PMID 31708917, 2019). "For instance, Bmal1 gene regulates the molecular system to prevent cancer progression in several tissues 47,49." (PMID 31523185, 2019). "A similar phenotype was uncovered when manipulations consisted of knocking out core clock genes (Per2 or Bmal1 (Arntl1)) in animals that develop spontaneous cancer (KrasLA2/+ mice)." (PMID 31773065, 2019). "In summary, our present research illustrates a novel insight into the circadian clock proteins, CLOCK and BMAL1, which can promote the proliferation, migration, and invasion of cancer cells by affecting the formation of F-actin." (PMID 30287810, 2018). "Consistent with this study, agonists of REV-ERB, which is the main suppressor of Bmal1 transcription, are lethal to cancer cells and oncogene-induced senescent cells." (PMID 30348208, 2018). "BMAL1 was proposed to have an inhibitory effect on cell cycle progression and invasion, suggesting it is protective in this type of cancer." (PMID 30348208, 2018). "While these studies used other cancer models to study the role of BMAL1, the findings are likely relevant to breast cancer." (PMID 29780357, 2018). "Although, there are studies on the role of Bmal1 in carcinogenesis using germline, conditional or tissue-specific knockouts, it is still not well understood how BMAL1 gene affects cancer-related biological events at the molecular level." (PMID 30375470, 2018). "On the other hand, CpG islands in the BMAL1 promoter of some cancer cell lines are hypermethylated and the BMAL1 gene is transcriptionally silenced." (PMID 28487473, 2017).